RN7SL794P (RNA, 7SL, cytoplasmic 794, pseudogene)
Gene: Miscellaneous RNA gene on chromosome 9 (99,185,587 to 99,185,866, reverse strand). Ensembl gene ENSG00000240235.
Homologues: Orthologues: chimpanzee Metazoa_SRP (97% identical), macaque Metazoa_SRP (93% identical). Paralogues in human: RN7SL1 (81% identical), RN7SL2 (81% identical), RN7SL3 (81% identical), RN7SL322P (80% identical), RN7SL187P (79% identical), RN7SL126P (79% identical), Metazoa_SRP (78% identical), RN7SL627P (78% identical), RN7SL769P (78% identical), RN7SL220P (78% identical), RN7SL517P (78% identical), RN7SL122P (77% identical), and 702 more.